FXYD3 (FXYD domain containing ion transport regulator 3)
Diseases named in the same sentence as FXYD3 in open-access papers (continued):
Sharing a sentence is not in itself a finding about the gene and the disease.
tumor (22 papers, 2011 to 2026). "Subsequently, in vitro and in vivo experiments demonstrated that FXYD3 expression was significantly upregulated in ICC tumor tissues and cell lines and was closely associated with tumor progression and poor prognosis." (PMID 41164952, 2026). "In conclusion, FXYD3 predicts a poor prognosis associated with hypoxia, pro-tumor TILs, and T cell exhaustion in KIRC." (PMID 35892856, 2022). "Taken together, FXYD3 is associated with poor prognosis in KIRC in relation to pro-tumor TME, potentially with hypoxia-related signaling, less NK cells, and exhausted CD8+ T cells." (PMID 35892856, 2022). "In conclusion, FXYD3 is an unfavorable prognostic biomarker associated with hypoxia, pro-tumor TILs, and T cell exhaustion." (PMID 35892856, 2022). "The ESTIMATE algorithm revealed that higher FXYD3 mRNA levels were associated with increased infiltration of immune cells and tumor purity." (PMID 35892856, 2022). "Overall, according to the network, MIR22HG regulates FXYD domain‐containing ion transport regulator 3 (FXYD3) through hsa‐mir‐613 and hsa‐mir‐24‐3p, and its downregulation may be associated with tumor formation." (PMID 38321787, 2024). "Furthermore, the algorithms discovered that FXYD3 mRNA levels were associated with tumor purity, multiple types of the tumor infiltrating lymphocytes (TILs) and several genes related to T cell exhaustion." (PMID 35892856, 2022). "An siFXYD3 nano‐delivery system (siFXYD3@PEP) for treating an orthotopic xenograft tumor model of ICC was developed to investigate the possibility of FXYD3 as a therapeutic target for anticancer treatment (left)." (PMID 41164952, 2026). "In vitro and in vivo experiments demonstrated that FXYD3 expression was upregulated in ICC tumor tissues and associated with tumor progression and unfavorable prognosis." (PMID 41164952, 2026). "Subsequently, we performed wound healing assays to examine the effect of FXYD3 knockdown on tumor cell migration and invasion." (PMID 41164952, 2026). "Subsequently, in an external dataset, FXYD3 was specifically overexpressed in tumor tissues in TCGA‐iCCA." (PMID 41164952, 2026). "FXYD3 knockdown resulted in a markedly reduced tumor burden, as evidenced by fewer tumors, smaller tumor volumes, and a decreased liver weight‐to‐body weight (LW/BW) ratio, compared to controls." (PMID 41164952, 2026). "TUNEL staining and Ki‐67 staining further confirmed that FXYD3 promotes tumor formation in nude mice." (PMID 41164952, 2026). "Conversely, mice injected with FXYD3 overexpressing HCCC‐9810 cells exhibited accelerated tumor growth, with increased mean tumor size and weight, compared to controls." (PMID 41164952, 2026). "The tumor growth rate was significantly inhibited while the average tumor weight and volume markedly decreased following the treatment of FXYD3‐overexpressing HCCC‐9810 cells with AZD1480." (PMID 41164952, 2026). "We examined the effect of FXYD3 on tumor growth in a mouse model of subcutaneously transplanted tumors to elucidate it's in vivo biological function." (PMID 41164952, 2026). "One study demonstrates that FXYD3 silencing does significantly slow down the proliferation of T3M4 PDAC cell lines, leading to the conclusion that FXYD3 expression potentiates tumour growth." (PMID 39783776, 2025). "FXYD3 has also been found to be overexpressed in PDAC tumours, and silencing this protein has been demonstrated to slow down the growth of PDAC cells." (PMID 39783776, 2025). "Herein, we present a study establishing the rate of immunohistochemically‐evaluated FXYD3 expression in chemotherapy‐naïve resected PDAC tumours." (PMID 39783776, 2025). "Corroborating the results obtained from the proteomic data analysis, the TNMplot database showed an increased expression of FXYD3 in tumor and metastatic tissue samples as compared to normal samples." (PMID 37047289, 2023).
tumor (continued). "ELDA analysis demonstrated that the knockdown of FXYD3 remarkably decreased the spheroid-forming ability in vitro and tumor-initiating ability in vivo, providing strong evidence to support the notion that FXYD3 plays a crucial role in CSCs." (PMID 37966117, 2023). "To understand the poor outcome in FXYD3 high KIRC patients, we examined the characteristics of the TME between FXYD3 high and low patients in terms of TILs, tumor purity, and abundance of stromal cells using the ESTIMATE algorithm." (PMID 35892856, 2022). "RT‐qPCR and Western blot analyses were conducted to determine the expression of let‐7i, KDM3A, DCLK1 and FXYD3 in tumours." (PMID 33350586, 2021). "Compared with mice injected with cells expressing si‐FXYD3, decreased lung tissue damage and the number of metastatic tumour nodules was found after the si‐FXYD3 + EV‐let‐7i‐mimic treatment." (PMID 33350586, 2021). "Intriguingly, our results illustrated that compared with model mice, tumours in nude mice treated by EV‐let‐7i‐mimic were notably reduced (p ˂ 0.05), whereas tumours in nude mice treated by si‐FXYD3 were considerably increased (p ˂ 0.05)." (PMID 33350586, 2021). "FXYD3 expression in the cytoplasm and/or normal epithelial membranes and tumor cells, and the staining in the cytoplasm and/or the membrane was heterogeneous and granulous." (PMID 25013464, 2014). "FXYD3 has been shown to be involved in tumor cell proliferation and to be downregulated by TGF-β signaling." (PMID 23251436, 2012). "Given that FXYD3 demonstrated potent anti‐tumor activity in vitro and in vivo, we hypothesized that combining FXYD3@PEP with first‐line chemotherapy would yield enhanced therapeutic efficacy." (PMID 41164952, 2026). "In addition, western blot analysis of 10 randomly selected paired ICC tissue samples demonstrated significantly elevated FXYD3 levels in tumor tissues compared to non‐tumor tissues." (PMID 41164952, 2026). "The analysis revealed that FXYD3 was markedly overexpressed in more aggressive tumor cells." (PMID 41164952, 2026). "FXYD3 expression was assessed in tumour specimens using immunohistochemistry." (PMID 39783776, 2025). "However, FXYD3 is expressed in the vast majority of PDAC tumours, and therefore its utility as a therapeutic target should continue to be explored." (PMID 39783776, 2025). "AGR2, FXYD3, TFF1, and MUC13 are associated with increased tumor grade." (PMID 39682235, 2024). "Furthermore, increased FXYD3 expression enables the Na+/K+ pump in the ancestor-like CSCs to resist ROS, enhancing tumor resilience." (PMID 37966117, 2023). "The in vitro experiments suggest FXYD3 can be involved in tumor proliferation." (PMID 35892856, 2022). "Moreover, we investigated the tumor microenvironment (TME) by evaluating the estimated TILs and immune-inhibitory gene expressions in association with FXYD3 expression." (PMID 35892856, 2022). "In total, FXYD3 could be involved in tumor cell behavior contributing to poor prognosis in multiple cancers." (PMID 35892856, 2022). "In addition, a growing body of evidence indicates that FXYD3 expression is upregulated in numerous different tumor tissues and tumor cell lines." (PMID 25013464, 2014). "Moreover, certain studies indicate that tumor malignancy is positively correlated with FXYD3 expression." (PMID 25013464, 2014). "Furthermore, we have found that overexpression of FXYD6 increases migration and proliferation in the human SMMC7721 cells, which agrees with the role of FXYD3 or FXYD5 overexpression in tumor progression." (PMID 24715268, 2014). "Notably, we found that the ductal cell markers and epithelial cell-specific markers reported previously, such as EPCAM, KRT18, SOX9, KRT19, MUC1, and FXYD3, were commonly expressed in the majority of clusters except for cluster 17, confirming tumor cell identity." (PMID 37324492, 2023).
tumor (continued). "The results demonstrated that the injection of FXYD3 knockdown HUCCT cells resulted in slower tumor growth, compared to controls, as evidenced by reduced mean tumor weight and smaller tumor volume." (PMID 41164952, 2026). "The targeted FXYD3 nano‐delivery system (siFXYD3@PEP) exhibited significant antitumor efficacy in spontaneous and transplanted tumor models and markedly enhanced the sensitivity of ICC to standard gemcitabine and cisplatin chemotherapy." (PMID 41164952, 2026). "Relationship between immunohistochemical FXYD3 expression and clinicopathological markers of PDAC tumour stage and grade." (PMID 39783776, 2025). "CRIP1 was specific to the tumor region, whereas BCAT1 and FXYD3 were confined to the stromal region." (PMID 39135097, 2024). "Compared with the normal group, the tumor group had higher expressions of MLPH, MISP, KDM6B, and FXYD3 genes." (PMID 35673567, 2022). "The present study demonstrates that FXYD3 is an unfavorable prognostic biomarker in KIRC with hypoxia, pro-tumor TILs, and multiple genes related to T cell exhaustion." (PMID 35892856, 2022). "Previous studies have reported that specific members of the FXYD protein family, including FXYD3 and FXYD5, play important roles in the pathogenesis of a number of tumor types." (PMID 24396454, 2014). "It has been reported that FXYD2, FXYD3 and FXYD5 are up-regulated in several types of tumors, leading to accelerated tumor growth and progression." (PMID 24715268, 2014). "Additionally, the targeted FXYD3 nano‐delivery system (siFXYD3@PEP) exhibited significant antitumor efficacy in spontaneous and transplanted tumor models and markedly enhanced the sensitivity of ICC to standard gemcitabine and cisplatin chemotherapy." (PMID 41164952, 2026). "Notably, the targeted FXYD3 nano‐delivery system (siFXYD3@PEP) exhibited significant antitumor efficacy in spontaneous and transplanted tumor models and markedly enhanced the sensitivity of ICC to standard gemcitabine and cisplatin chemotherapy." (PMID 41164952, 2026). "The results demonstrated that the combination of FXYD3@PEP with gemcitabine and cisplatin exerted a more pronounced antitumor effect than FXYD3@PEP alone or gemcitabine and cisplatin combination therapy in nude mice and spontaneous tumor formation mouse models." (PMID 41164952, 2026). "Furthermore, the mechanism by which FXYD3‐driven IFN‐I response precisely modulates the function of immune cells—such as T cells and NK cells—within the tumor microenvironment requires additional investigation." (PMID 41164952, 2026). "In addition, fetal-I tumor organoids (hepatic-intermediate) expressed markers related to tumor progression and invasion, including TSPAN8, CKB, UCA1, and FXYD3." (PMID 39567475, 2024). "We detected the presence of miR‐433, FXYD3, p‐AKT and p‐p85 expressions in tumour tissues, which demonstrated that KDM5A silencing led to significant increase in miR‐433 and reduction in expression levels of FXYD3, p‐AKT and p‐p85 in tumour tissues (P < .05)." (PMID 33621431, 2021). "Inspired by the close correlation between FXYD3/FXYD5 and tumor progression, we supposed that FXYD6 may be also involved in tumor malignancy." (PMID 24715268, 2014). "The present study showed the low expression of TGF-β in FXYD3 low patients, suggesting that infiltrated neutrophils might not gain a pro-tumor phenotype." (PMID 35892856, 2022). "We found that phospho-Ser536-p65 expression was positively related to TEM1, FXYD-3, PRL, p73 and MAC30 in tumours that received RT, however there were no such relationships in the non-RT group." (PMID 22933966, 2011).
FXYD3 also shares sentences with these, for which no sentence is quoted: hepatocellular carcinoma (4 papers); diabetes (2); cardiac hypertrophy (1); chronic pancreatitis (1); diabetic cardiomyopathy (1); ductal carcinoma (1); esophageal squamous cell carcinoma (1); Hypomagnesemia (1); Insulin resistance (1); intrahepatic cholangiocarcinoma (1); melanoma (1); ovarian tumors (1); renal cell carcinoma (1); schizophrenia (1); stomach cancer (1); thyroid cancer (1); urothelial carcinoma (1).